SRF (serum response factor)
Description:
SRF is a transcription factor that binds to the serum response element (SRE), a short sequence of dyad symmetry located 300 bp to the 5' of the site of transcription initiation of some genes (such as FOS). Together with MRTFA transcription coactivator, controls expression of genes regulating the cytoskeleton during development, morphogenesis and cell migration. The SRF-MRTFA complex activity responds to Rho GTPase-induced changes in cellular globular actin (G-actin) concentration, thereby coupling cytoskeletal gene expression to cytoskeletal dynamics. Required for cardiac differentiation and maturation.
Synonyms: MCM1
Tractability: No criterion of Open Targets' tractability assessment is met for any kind of drug.
Target class: Transcription factor
Gene: Protein-coding gene on chromosome 6 (43,171,269 to 43,181,506, forward strand). Ensembl gene ENSG00000112658.
Subcellular location: Nucleus
Subcellular location (Human Protein Atlas): Nucleoplasm
Pathways (Reactome):
Signal Transduction: Estrogen-dependent nuclear events downstream of ESR-membrane signaling; NGF-stimulated transcription; RHO GTPases Activate Formins
Developmental Biology: Cardiogenesis
Gene expression (Transcription): Regulation of NPAS4 gene transcription
Gene Ontology:
Molecular function: DNA-binding transcription activator activity, RNA polymerase II-specific; DNA-binding transcription factor activity; DNA-binding transcription factor binding; protein binding; protein homodimerization activity; RNA polymerase II cis-regulatory region sequence-specific DNA binding; sequence-specific double-stranded DNA binding; serum response element binding; DNA-binding transcription factor activity, RNA polymerase II-specific; primary miRNA binding; chromatin binding; chromatin DNA binding; cis-regulatory region sequence-specific DNA binding; DNA binding; histone deacetylase binding; protein dimerization activity; RNA polymerase II-specific DNA-binding transcription factor binding; sequence-specific DNA binding
Biological process: cardiac muscle cell myoblast differentiation; cell migration involved in sprouting angiogenesis; cellular senescence; negative regulation of amyloid-beta clearance; positive regulation of cell differentiation; positive regulation of miRNA transcription; positive regulation of smooth muscle contraction; positive regulation of transcription by RNA polymerase II; positive regulation of transcription initiation by RNA polymerase II; response to cytokine; response to hormone; response to hypoxia; trophectodermal cell differentiation; actin cytoskeleton organization; angiogenesis involved in wound healing; heart development; heart looping; muscle cell cellular homeostasis; negative regulation of miRNA transcription; neuron development; regulation of smooth muscle cell differentiation; response to toxic substance; cellular response to glucose stimulus; in utero embryonic development; long-term memory; and 5 more
Cellular component: nucleoplasm; nucleus; cytoplasm; chromatin
Genetic constraint (gnomAD): Loss-of-function variants: 7 observed, 36.75 expected, observed/expected ratio (o/e) 0.19, 90% interval 0.11 to 0.36. The upper end of that interval is the gene's LOEUF score, 0.36, which puts it in group 1 of 6, group 1 being the genes least tolerant of losing a copy. Missense variants: 395 observed, 649.68 expected, observed/expected ratio (o/e) 0.61, 90% interval 0.56 to 0.66. Synonymous variants: 285 observed, 286.38 expected, observed/expected ratio (o/e) 1, 90% interval 0.9 to 1.1.
Gene-disease validity (ClinGen):
ClinGen rates the evidence that SRF causes each of these diseases.
congenital heart disease (autosomal dominant): Limited. A heart disease that is present at birth.
Homologues: Orthologues: chimpanzee SRF (99% identical), macaque SRF (99% identical), pig SRF (97% identical), dog SRF (97% identical), rat Srf (97% identical), mouse Srf (96% identical), rabbit SRF (96% identical), guinea pig SRF (73% identical), tropical clawed frog srf (71% identical), zebrafish srfb (32% identical), Caenorhabditis elegans unc-120 (23% identical). Paralogues in human: MEF2D (18% identical), MEF2A (17% identical), MEF2C (17% identical), MEF2B (13% identical).
Diseases named in the same sentence as SRF in open-access papers:
SRF is named in the same sentence as 207 diseases in open-access papers, as found by Europe PMC text mining. Sharing a sentence is not in itself a finding about the gene and the disease. The quoted sentences say what the papers report.
breast carcinoma (44 papers, 2011 to 2026). "Furthermore, Kaplan-Meier analysis revealed a significant association between high-level expression of SRF and shorter overall survival and distant metastasis-free survival in breast cancer patients with a high CRP2 expression profile." (PMID 37266453, 2023). "Our findings suggest that miR-564 is a potential tumor suppressor that regulates both PI3K and MAPK signaling by directly targeting a network of genes (AKT2, GNA12, GYS1 and SRF) linked to these pathways, and thus controls breast cancer cells proliferation, EMT, migration and invasion." (PMID 27600857, 2016). "Previous studies highlight that SRF is a potential transcriptional regulator of TAZ(WWTR1) in breast cancer." (PMID 37385752, 2023). "The clinical significance of SRF expression in basal breast cancer was evaluated by Kaplan-Meier analysis using publicly available transcriptomics data sets." (PMID 37266453, 2023). "The interaction of serum response factor (SRF) with YAP mediated the expression of numerous mammary stem cell signature genes to induce the mammary stem cell-like properties in basal-like breast cancer." (PMID 37081542, 2023). "Abundantly expressed SRF plays a pivotal role in the development of epithelial cancers, such as gastric, prostate, renal cell, esophageal squamous cell, cervical, and breast cancers." (PMID 36831659, 2023). "Our immunoprecipitation and PLA data support the interaction between CRP2 and SRF in breast cancer cells." (PMID 37266453, 2023). "To confirm the regulatory role of SRF in MMP gene expression in breast cancer cells, we used two different SRF-targeting siRNAs to knock down SRF and quantified the levels of MMP-9 and MMP-13 mRNAs using real-time RT-qPCR." (PMID 37266453, 2023). "Six CDM genes (SRF, RAD51, PMF1, EXOSC3, EXOC1, and TSEN54) were found to be associated with the prognosis of breast cancer samples." (PMID 35096059, 2022). "The univariate and multivariate Cox regression analysis revealed that six CDM genes (SRF, RAD51, PMF1, EXOSC3, EXOC1 and TSEN54) were associated with the survival of patients with breast cancer." (PMID 35096059, 2022). "In breast cancer, MKL1 together with SRF promotes the expression of IL-11 to enhance breast cancer stemness and metastasis." (PMID 33500406, 2021). "In conclusion, combined analyses of AKT2, GNA12, GYS1 and SRF expression mimic the effects of miR-564 on tumor progression and survival of breast cancer patients." (PMID 27600857, 2016). "TAZ is a direct target gene of MRTF/SRF in breast cancer in which the mRNA expression level of TAZ is correlated with the MRTF nuclear localization and the classic direct target genes of MRTF/SRF." (PMID 26885614, 2016). "Both Hippo pathway and MRTF/SRF pathway are the downstream effectors of heregulin activation in breast cancers." (PMID 26885614, 2016). "MRTF/SRF pathway was first delineated in the fibroblast and then found to be involved in the cancer metastasis including breast cancer." (PMID 26885614, 2016). "TAZ mRNA level is correlated with nuclear localization of MRTF in breast cancer cells and the mRNA level of MRTF/SRF direct target genes in breast cancers, indicating the correlation between MRTF/SRF activity and TAZ expression." (PMID 26885614, 2016). "RhoA- and RhoC-induced gene transcription via the actin-regulated transcriptional co-activator megakaryocytic leukemia (MKL) and serum response factor (SRF) drive metastasis in breast cancer and melanoma." (PMID 27600078, 2016). "High expression level of TAZ mRNA was associated with basal-like breast cancers, similarly, the expression level of MRTF/SRF target genes were higher in the basal-like breast cancers compared to other subtypes of breast cancers." (PMID 26885614, 2016). "Recently, MKL and SRF were shown to play a key role in metastasis in melanoma and breast cancer xenograft systems providing a strong link to the transcriptional effects of RhoA or RhoC in these processes." (PMID 27600078, 2016).
breast carcinoma (continued). "SRF–YAP–IL6 signalling is enriched in MaSC/progenitor cell-like basal-like breast cancer (BLBC) in patients' samples and is required for generation of cancer stem cells (CSCs) and cancer relapse specifically in BLBC." (PMID 26671411, 2015). "We further examined the significance of the SRF–YAP–IL6 signalling axis in vivo using the 4T1 breast cancer cell line syngeneic graft model." (PMID 26671411, 2015). "Nedd9 induction is necessary to establish a positive feedback loop that integrates TGF-beta/Smad and Rho-actin-SRF signalling and drives the expansion of tumour-initiating cells, selectively in claudin low breast cancer, upon TGF-beta stimulation." (PMID 25606587, 2014). "We discovered a breast cancer-specific set of genes including tenascin-C, which is regulated by Mkl1 in a SAP domain-dependent, serum response factor-independent manner and is strongly implicated in cell proliferation, cell motility and cancer." (PMID 24495796, 2014). "A number of researchers have reported that SRF is highly expressed in tumors, including colorectal cancer, hepatocelluar carcinoma, breast cancer and thyroid carcinoma." (PMID 23426188, 2013). "Overexpression of SRF in hepatocellular carcinoma and breast cancer accelerates cell migration and invasion, and there is a subsequent acquisition of mesenchymal phenotypes due to the expression of a mesenchymal marker (vimentin)." (PMID 23426188, 2013). "LMO7, also amplified in our samples, was shown to mediate cell-specific activation of Rho-MRTF_SRF pathway, where it plays an important role in breast cancer cells migration." (PMID 22879877, 2012). "A recent report implicates MYH9 (NMHC-IIA) as a target of SRF, which contributes to invasion and metastasis in breast cancer." (PMID 21533124, 2011). "SRF is a potential prognostic biomarker of different types of cancers (such as breast cancer, prostate cancer, and gastric cancer) and may also represent a therapeutic target in the treatment of these cancers." (PMID 37893423, 2023). "In addition, the prognosis of patients with breast cancer can be improved by promoting tamoxifen sensitivity in breast cancer cells by knocking down LINC00152 to inhibit SRF." (PMID 36033524, 2022). "Moreover, MRTF/SRF was reported to induce TAZ transcription in breast cancer cells in response to Heregulin β134." (PMID 32019974, 2020). "The target genes of the SRF(-) regulatory module that are over repressed by SRF may be novel candidates for promoting the stemness of basal-like type breast cancers." (PMID 31296219, 2019). "In addition, modulation of MKL/SRF dependent metastasis networks in both breast cancer and melanoma cell lines with our compound highlights the importance of pharmacologic inhibitors of this pathway as potential future therapeutics in cancer biology." (PMID 27600078, 2016). "All these data suggest a transcriptional regulation of TAZ by MRTF/SRF in breast cancers." (PMID 26885614, 2016). "Here, we found high expression of TAZ in breast cancer was correlated with high mRNA level of MRTF/SRF target genes indicating the dysregulation of TAZ in breast cancer could also be due to the dysregulation of TAZ transcription by MRTF/SRF." (PMID 26885614, 2016). "High SRF–YAP/TAZ expression is correlated with IL6-enriched MaSC/basal-like breast cancer (BLBC)." (PMID 26671411, 2015). "Indeed, an expression analysis of various breast cancer cell lines revealed that SRF, YAP/TAZ and IL6 are all upregulated in BLBC cell lines compared with other types of breast cancer." (PMID 26671411, 2015). "Targeting CRP2 could offer an opportunity to selectively target SRF in breast cancer cells." (PMID 37266453, 2023). "Furthermore, MRTF/SRF target genes' expression was positively associated with basal marker (CDH3), but negatively correlated with luminal marker (ESR1), suggesting that the activity of MRTF/SRF is higher in basal-like breast cancers than other subtypes." (PMID 26885614, 2016).
breast carcinoma (continued). "In breast cancer cells, lncRNA CYTOR binds to miR-125-5p, downregulating its levels and promoting the expression of serum response factor (SRF), thereby increasing resistance to tamoxifen (TAM)." (PMID 40078288, 2025). "Its overexpression also enhances the EMT (Epithelial-mesenchymal transition) of breast cancer cells by increasing cytoskeleton dynamics and activating mesenchymal lineage transcription factors, such as MKL1 and SRF." (PMID 34113576, 2021). "In basal like breast cancer cells, serum response factor (SRF) interacts with YAP and induces IL-6 expression, which promotes stemness of basal like breast cancer cells." (PMID 32596154, 2020). "In a follow-up publication the same group identified a set of breast cancer specific genes, including TNC, that are regulated by MRTF-A in an SRF-independent manner." (PMID 28536630, 2016). "MRTF/SRF signaling promotes TAZ gene expression and protein abundance downstream of activation by heregulin β1 in breast cancer cells." (PMID 28536630, 2016). "Our present study demonstrates a distinct regulatory role of miR-564 in breast cancer progression by direct targeting of a network of genes, namely AKT2, GNA12, GYS1 and SRF that leads to simultaneous inhibition of PI3K and MAPK pathways." (PMID 27600857, 2016). "To extend our findings to human breast cancer, we examined expression levels of SRF, YAP/TAZ and IL6 in human breast cancer patients by analysing microarray data from various breast cancer study cohorts." (PMID 26671411, 2015). "SRF, YAP, TAZ (WWTR1) and IL6 are consistently upregulated in BLBC, normal-like breast cancer and claudin-low subtypes." (PMID 26671411, 2015). "Finding how to switch the mode of action of Mkl1 between SRF transactivation versus its SAP-dependent transcriptional activity is a subject of ongoing research in our lab that in future may help with the development of new therapeutic interventions for breast cancer." (PMID 24495796, 2014). "Importantly, SRF interacts with YAP in mammary epithelial and breast cancer cells to drive cancer stemness." (PMID 37385752, 2023). "Additionally, binding of miR-125a-5p to LINC00152 was shown to increase the expression of the SRF gene by resulting in activation of Hippo and MAPK signaling pathways in human breast cancer." (PMID 35563834, 2022). "Similarly, hsa-miR-206, which inhibits self-renewal and invasiveness of breast cancer cells, also targets TWF1, which enhances MKL1 and SRF that in turn, promoting IL-11 expression." (PMID 35163731, 2022). "Although we have shown that SRF and YAP are necessary for induction of MaSC-like properties in mammary epithelial cells and breast cancer cell lines, it should be noted that high expression of these two proteins is not sufficient to fully induce MaSC-like properties." (PMID 26671411, 2015). "We again confirmed the importance of SRF and YAP/TAZ in breast cancer stemness using tissue arrays." (PMID 26671411, 2015). "Finally, we show that this high SRF expression enables YAP to more efficiently induce IL6 and stemness in BLBC compared with luminal-type breast cancer." (PMID 26671411, 2015). "Consistent with a role for MRTF-A–SRF signaling in mediating P-cad functional effects in fully transformed cells, MRTF-A/SRF has been shown to play an important role in the metastatic lung colonization of breast cancer cells and in drug resistance of basal cell carcinoma." (PMID 36808468, 2023). "Notably, our findings, in glia, implicate Drosophila Profilin and SRF signalling in MRL-mediated tumour dissemination, whereas interactions between Lpd and Ena/VASP and Scar/WAVE have been reported to be critical in the invasion of breast cancer cells." (PMID 28346426, 2017).
breast carcinoma (continued). "Moreover, CYTOR is upregulated in tamoxifen-resistant breast cancer cell lines derived from MCF7, and CYTOR functions as a ceRNA by sponging miR-125a-5p, and upregulates a target of miR-125a-5p, the serum response factor (SRF), which promotes the tamoxifen resistance and cell proliferation." (PMID 32486413, 2020). "ELK1, but not SRF or STAT3, was reported to regulate both the basal and epidermal growth factor induced MCL1 transcription in breast cancer cells." (PMID 40075071, 2025). "Intrigued by our finding that SRF, which is essential for YAP-induced MaSC-like properties, is highly expressed in BLBC but not in luminal-type breast cancer, we investigated the possibility that YAP might activate IL6 expression and MaSC-like properties specifically in BLBC." (PMID 26671411, 2015).